POLR2A (RNA polymerase II subunit A)
Diseases named in the same sentence as POLR2A in open-access papers (continued):
Sharing a sentence is not in itself a finding about the gene and the disease.
colorectal cancer (11 papers, 2019 to 2025). A primary or metastatic malignant neoplasm that affects the colon or rectum. "Downregulation of POLR2A expression in colorectal cancer inhibited the proliferation and survival of tumor cells." (PMID 33001583, 2020). "It was shown that low doses of the α-amanitin-conjugated anti-epithelial cell adhesion molecule (EpCAM) antibody lead to complete tumor regression in mouse models of human colorectal cancer with hemizygous deletion of POLR2A." (PMID 31398954, 2019). "POLR2A is a major regulator of the expression of thousands of eukaryotic genes, and its inhibition has been shown to affect proliferation, survival, and tumorigenic capacity in colorectal cancer cells." (PMID 40863222, 2025). "Furthermore, in triple negative breast cancer (TNBC) and colorectal cancer (CRC), inhibition of POLR2A has a selective inhibitory effect on the growth of tumors with loss of POLR2A hemizygotes." (PMID 34899822, 2021). "Therefore, POLR2A is promisingly expected to become a new target for colorectal cancer or breast cancer treatment." (PMID 33001583, 2020). "As a pilot experiment to demonstrate MOSAICA’s potential for multiomics profiling, we utilized MOSAICA to detect 2 protein targets, Tubulin and Vimentin, and 2 mRNA targets, POLR2A and MTOR in colorectal cancer SW480 cell culture samples." (PMID 35013281, 2022). "Loss of NAT2, a non-essential enzyme involved in drug metabolism, in colorectal cancers emerged as an attractive target conceptually different from synthetic lethality (ENO2, PRMT5, ME3) or targeting genes essential for cell survival (POLR2A, RPA70, or PSMC2)." (PMID 32161261, 2020).
breast cancer (8 papers, 2011 to 2025). A primary or metastatic malignant neoplasm involving the breast. "The other two signals were at BRCA1, coding for a DNA repair protein and associated with increased breast cancer risk, and POLR2A, encoding a subunit of RNA polymerase II." (PMID 40287427, 2025). "The notion of increased vulnerability is supported by reports showing that reduced expression of POLR2A in del17p prostate and breast cancer cells is associated with enhanced sensitivity to the fungal toxin α-amanitin." (PMID 39966556, 2025). "According to research, POLR2A is crucially involved in the pathogenesis of breast cancer and glioblastoma." (PMID 39719443, 2024). "High expression of POLR2A predicts poor prognosis in breast cancer patients, and selective targeting of POLR2A can inhibit cell growth." (PMID 33001583, 2020). "This review has already discussed how POLR2A LOH leads to lower expression of RNA polymerase II (RNAP2) in del17p prostate and breast cancer cells, and how this renders such cells more sensitive to the cytotoxic effects of the fungal toxin α-amanatin." (PMID 39966556, 2025). "Moreover, high expression of cdc7 and RNA polymerase II Subunit A (POLR2A), the direct target of CDK9, is significantly correlated with poor metastasis-free survival in a cohort of breast cancer patients." (PMID 31262335, 2019).
melanoma (8 papers, 2018 to 2025). A malignant, usually aggressive tumor composed of atypical, neoplastic melanocytes. "Prognostic analysis results showed that high expression levels of hsa-miR-550a-3p, CDK2 and POLR2A and low expression levels of hsa-miR-150-5p in melanoma patients were associated with significantly reduced overall survival." (PMID 33313406, 2020). "Prognostic correlation analysis of cutaneous melanoma with molecular markers found that high expression of hsa-miR-500a-3p, CDK2 and POLR2A genes or low expression of hsa-miR-150-5p can significantly reduce OS in melanoma patients." (PMID 33313406, 2020). "Similar as in CRC, melanoma cell lines with a hemizygous loss of POLR2A (i.e., IGR-37, SK-MEL-2) had significantly lower levels of POLR2A mRNA and protein than the POLR2A copy neutral cell lines A375-P and UACC-62." (PMID 31123282, 2019). "Shutdown of this signaling pathway in melanoma cell lines leads to a decrease of POLR2A stability and therefore diminishes its protein levels over time." (PMID 31123282, 2019). "High expression of CDK2 and POLR2A genes in melanoma patients significantly reduced OS." (PMID 33313406, 2020). "Since inhibition of oncogenic BRAFV600E signaling in melanoma cells decreased POLR2A stability, we investigated whether the RNA polymerase II inhibitor α-amanitin might exhibit synergistic effects in combination with PLX4720." (PMID 31123282, 2019). "Only URI1 interaction with POLR2A consistently decreased in three out of four melanoma cell lines." (PMID 31123282, 2019). "Therefore, we treated the three BRAFV600E-mutated melanoma cell lines A375-P, UACC-62 and WM-266-4 either with α-amanitin alone or in combination with PLX4720 for 72 hours and assessed POLR2A protein levels as well as PARP and Caspase-3 cleavage by western blot." (PMID 31123282, 2019). "Pre-treatment of melanoma cell lines with MAPK inhibitors significantly reduced IC50 values to α-amanitin, creating a state of collateral vulnerability similar to POLR2A hemizygous deletions." (PMID 31123282, 2019). "Specifically, we applied a mRNA panel consisting of KI67 (indicative of cell proliferation), POLR2A, BRCA1, MTOR, NCOA2, and NCOA3 to highly scattering and autofluorescent human melanoma skin biopsy FFPE tissues obtained from and characterized by the UCI Dermatopathology Center." (PMID 35013281, 2022).
lung carcinoma (7 papers, 2010 to 2025). "The SNP (rs2071504 C) and SNP (c.2292C > T, rs2228130) in POLR2A was associated with poor survival outcomes in lung cancer, suggesting the potential carcinogenic role of POLR2A in lung cancer." (PMID 33001583, 2020). "Following the knockout of p130Cas in lung cancer cells, including H1975 and H1299 cells, a significant decrease in POLR2A expression was observed." (PMID 40362257, 2025). "In lung cancer tissues, the expression of POLR2A and p130Cas was significantly higher than matched normal tissues." (PMID 40362257, 2025). "High expression of either BCAR1 or POLR2A predicted poor prognosis in 54 lung cancer cases in early stage." (PMID 33001583, 2020). "Based on these findings, we speculate that BCAR1 can, at the very least, indirectly upregulate POLR2A expression, which has critical biological functions leading to cell proliferation, cell growth, and subsequent poor prognosis in lung cancer cases." (PMID 33001583, 2020). "Our findings revealed that in lung cancer tissues or cells, five transcription factors—FOXA1, CEBPB, CTCF, LMNB1, and POLR2A—concurrently regulate the transcription of COL5A1, MMP1, and SERPINE1." (PMID 39551792, 2024). "POLR2A and BCAR1 were significantly increased in lung cancer tissues as compared with matched normal tissues." (PMID 33001583, 2020). "High expression of POLR2A was significantly positively correlated to BCAR1 overexpression and predicted poor prognosis in 54 lung cancer cases." (PMID 33001583, 2020). "Fortunately, we obtained four hub genes (MAPK3, MOV10, XAB2, and POLR2A), which potentially interact with BCAR1 and play carcinogenetic roles in lung cancer." (PMID 33001583, 2020). "We analysed 12 SNPs in POLR2A, RNASEN and DICER1 genes in 1984 cases and 2073 controls from the Environment And Genetics in Lung cancer Etiology (EAGLE) study." (PMID 21102586, 2010). "None of the investigated polymorphisms in POLR2A, RNASEN and DICER1 showed significant association with lung cancer risk or lung cancer survival either overall or by subgroups of histology or smoking status." (PMID 21102586, 2010).
gastric cancer (5 papers, 2021 to 2025). A primary or metastatic malignant neoplasm involving the stomach. "However, the biological role and underlying molecular mechanism of POLR2A in gastric cancer (GC) are still unclear." (PMID 34899822, 2021). "Notably, POLR2A is highly expressed in several malignancies—including gastric cancer, non-small cell lung cancer, and clear cell renal cell carcinoma—where it has been implicated in tumor progression." (PMID 40854914, 2025). "POLR2A is markedly upregulated in gastric cancer (GC) tissues compared with adjacent non-tumor tissue, and its elevated expression correlates with larger tumor size, deeper invasion, and poorer prognosis." (PMID 41487511, 2025).
glioblastoma (5 papers, 2023 to 2025). The most malignant astrocytic tumor (WHO grade IV). "In these roles, circular POLR2A isoforms promote proliferation, migration, and therapy resistance in glioblastoma and clear-cell renal cell carcinoma by acting as miRNA sponges or by scaffolding protein complexes that activate pathways such as ERK." (PMID 41487511, 2025). "In cancer, POLR2A is frequently overexpressed across tumor types, including breast, lung, colon carcinomas, and glioblastomas." (PMID 41487511, 2025). "For instance, in breast cancer and glioblastoma (GBM), POLR2A levels showed only minor variation, whereas pronounced differences emerged at the protein level." (PMID 41487511, 2025). "In glioblastoma (GBM), lactylation of histone H3 increases the expression of LINC01127, which directs polymerase II (POLR2A) to the mitogen-activated protein kinase kinase kinase kinase 4 (MAP4K4) promoter region." (PMID 40584966, 2025).
viral infection (5 papers, 2020 to 2026). "Notably, the C-terminal domain of the large subunit of RNA polymerase II (RNAPII), POLR2A, is extensively phosphorylated, and its phosphorylation is significantly reduced upon CDK1 inhibition during viral infection." (PMID 41827841, 2026). "Recognizing this functional overlap between viral infection and tumor biology opens new therapeutic opportunities: oncolytic viruses and transcription-targeted agents may be strategically leveraged to disrupt tumor-specific vulnerabilities driven by the POLR2A/RPB1 axis." (PMID 41487511, 2025). "As expected, the PA-X-deficient virus did not cause significant downregulation of ACTB and G6PD transcripts compared to mock-infected cells, and the decrease in POLR2A and MALAT1 transcript was weaker although not significantly different from the WT virus infection." (PMID 38629840, 2024).
developmental delay (4 papers, 2021 to 2024). "Notably, POLR2A variants have been associated with a recently described neurodevelopmental syndrome with infantile-onset hypotonia and developmental delay with milder phenotypes attributed to haploinsufficiency, and a phenotype that shares overlapping features with SETBP1-HD." (PMID 39350244, 2024).
lung adenocarcinoma (4 papers, 2020 to 2025). A carcinoma that arises from the lung and is characterized by the presence of malignant glandular epithelial cells. "In lung adenocarcinoma, POLR2A expression strongly correlates with BCAR1 (breast cancer antiestrogen resistance protein 1) overexpression and with unfavorable clinical outcomes." (PMID 41487511, 2025). "Ultimately, we validated the correlated expressions of BCAR1 and a selected hub gene, RNA polymerase II subunit A (POLR2A), in 54 lung adenocarcinoma tissues, as well as in H1975 and H1299 cells." (PMID 33001583, 2020). "MOV10, encoding Mov10 RISC complex RNA helicase, was reported to be highly expressed with POLR2A, MAPK3, and XAB2 in 95% of 54 lung adenocarcinoma (LUAD) cases with poor prognosis." (PMID 34616428, 2021). "High expression of POLR2A, MAPK3, MOV10, and XAB2 predicted poor prognosis in lung adenocarcinoma, as verified by the K‐M plotter database." (PMID 33001583, 2020). "POLR2A and BCAR1 were significantly increased in lung adenocarcinoma tissues compared to adjacent normal tissues (1.090 ± 0.082 vs. 0.746 ± 0.236, P < 0.05 and 0.810 ± 0.090 vs. 0.589 ± 0.156, P < 0.05, respectively)." (PMID 33001583, 2020). "The K‐M plotter database indicated that high expression of POLR2A, MAPK3, MOV10, and XAB2 predicted poor prognosis in lung adenocarcinoma." (PMID 33001583, 2020).
ovarian carcinoma (4 papers, 2016 to 2025). A malignant neoplasm originating from the surface ovarian epithelium. "The composition of cancer types differed between copy number states for POLR2A, with higher proportions of breast and ovarian cancer in HeZD compared to CNN samples, which likely reflects increased copy number instability in these cancers." (PMID 28027311, 2016). "This disruption destabilizes the POLR2A protein, resulting in the inhibition of GDF15 transcription and a significant reduction in GDF15 expression and secretion in ovarian cancer cells." (PMID 39899667, 2025). "Mechanistic studies revealed that circMETTL6 inhibits ovarian cancer progression by recruiting the NONO protein, disrupting its interaction with POLR2A, and subsequently suppressing GDF15 transcription." (PMID 39899667, 2025). "CircMETTL6 binds to non-POU domain containing octamer-binding protein (NONO) and inhibits the binding of NONO to RNA polymerase II subunit A (POLR2A), which results in the suppression of ovarian cancer progression." (PMID 40710359, 2025). "Restoration of GDF15 expression can rescue the inhibited cell proliferation and metastasis caused by circMETTL6 overexpression, underscoring the critical role of circMETTL6 in disrupting NONO/POLR2A‐mediated GDF15 upregulation and subsequent ovarian cancer progression." (PMID 39899667, 2025).
diabetes (3 papers, 2018 to 2025). "qRT-PCR analysis showed that Fus, Hnrnpa2b1, Canx, Calr, and Polr2a were the significant difference in mRMVECs and Fus, Hnrnpa2b1, Canx, and Calr were the significant difference in the diabetic mouse model with DR (two months) compared to control groups." (PMID 35308095, 2022). "POLR2A, a subunit of RNA polymerase II (Pol II) can induce the expression of Cox2, S100A4/FSP-1 and vimentin genes in renal, which contributes to diabetes-mediated chromatin turnover and promotes transcriptional changes in diabetic kidneys." (PMID 30521536, 2018).
epilepsy (3 papers, 2022 to 2025). A brain disorder characterized by episodes of abnormally increased neuronal discharge resulting in transient episodes of sensory or motor neurological dysfunction, or psychic dysfunction. "POLR2A-related syndrome associated with epilepsy and mental retardation is caused by specific variants of a mutation in the largest subunit of RNA polymerase II." (PMID 40358185, 2025). "Future studies should explore whether patients with mild autistic features +/− epilepsy in the absence of intellectual disability might harbor POLR2A variants." (PMID 35328024, 2022).
glioma (3 papers, 2019 to 2024). A benign or malignant brain and spinal cord tumor that arises from glial cells (astrocytes, oligodendrocytes, ependymal cells). "This will enhance the translation of a number of key genes associated with malignant progression of gliomas, such as c-Myc, NRF2, TERT, POLR1A, and POLR2A." (PMID 30936423, 2019). "Among these TFs, CTCF, POLR2A, SIN3A, and SPI1 concurrently regulated all five prognostic genes in glioma." (PMID 39491527, 2024).
schizophrenia (3 papers, 2019 to 2023). A major psychotic disorder characterized by abnormalities in the perception or expression of reality. "Our study identified the plausible causal variants for schizophrenia and revealed the gene regulatory mechanisms affected by schizophrenia risk SNPs (including widespread disruption of POLR2A and CTCF binding)." (PMID 30737407, 2019). "Fourth, our study revealed new gene regulatory mechanisms affected by schizophrenia risk SNPs, including widespread disruption of POLR2A and CTCF binding." (PMID 30737407, 2019). "Our study reveals gene regulatory mechanisms affected by schizophrenia risk SNPs (including widespread disruption of POLR2A and CTCF binding) and identifies target genes for mechanistic studies and drug development." (PMID 30737407, 2019). "Binding of CTCF and POLR2A were frequently disrupted by schizophrenia risk SNPs." (PMID 30737407, 2019). "Forty SCZ risk SNPs disrupted binding of POLR2A, implying disruption of POLR2A binding may represent a common mechanism that schizophrenia risk variants exert their effect." (PMID 30737407, 2019). "Only one study reports that the missense schizophrenia risk variant rs1801311 (located in the 1st exon of NDUFA6 gene) can disrupt the binding of YY1, TAF1, and POLR2A." (PMID 36680208, 2023). "Genetic risk factors that overlap with TF-binding sites for USF1, NFIC, and POLR2A have been identified in relation to schizophrenia and MDD." (PMID 36386175, 2022).
Secretory Meningioma (3 papers, 2023 to 2025). A WHO grade I meningioma characterized by the presence of epithelial differentiation and numerous intracellular PAS positive bodies that are rich in glycogen. "Mutations in AKT1, KLF4, POLR2A or SMO were mostly detected in meningothelial or transitional meningioma, except for three cases: one case of angiomatous meningioma with KLF4 mutation, one case of secretory meningioma with KLF4 mutation and one case of psammomatous meningioma with AKT1 mutation." (PMID 40815185, 2025).
acute myeloid leukemia (2 papers, 2021 to 2025). Acute myeloid leukemia (AML) is a group of neoplasms arising from precursor cells committed to the myeloid cell-line differentiation. "A comparative analysis of POLR2A expression across multiple cancer types, conducted using the GEPIA2 platform, revealed substantial upregulation of POLR2A in malignancies such as acute myeloid leukemia and thymoma." (PMID 41487511, 2025). "In acute myeloid leukemia (LAML), both POLR2A and its catalytic subunit RPB1 are aberrantly activated, with RPB1 levels positively correlating with tumor burden and poor outcome." (PMID 41487511, 2025). "Similarly, POLR2A was highly expressed in acute myeloid leukemia (AML) cells and tissue samples, and positively correlated with the malignant proliferation of leukemia cells." (PMID 34899822, 2021).
cardiomyopathy (2 papers, 2010 to 2023). A disease of the heart muscle or myocardium proper. "The most stable reference genes were Rpl32, Gapdh and Polr2a in mouse post-infarction heart failure, Polr2a, Rpl32 and Tbp in rat post-infarction heart failure and Rpl32 and Pgk1 in human heart failure (ischemic disease and cardiomyopathy)." (PMID 20331858, 2010). "In the set of tested reference genes, the most stable reference genes were Rpl32, Gapdh and Polr2a in mouse post-infarction heart failure, Polr2a, Rpl32 and Tbp in rat post-infarction heart failure and Rpl32 and Pgk1 in human heart failure (ischemic disease and cardiomyopathy)." (PMID 20331858, 2010).
endometriosis (2 papers, 2025). The growth of functional endometrial tissue in anatomic sites outside the uterine body. "The results indicated that 13 TFs were identified in both SLE and endometriosis, and 6 of them (EP300, TCF12, CTCF, POLR2A, CEBPB and NFIC) can act on four potential co-diagnostic genes simultaneously." (PMID 39744159, 2025).